CREB5 (cAMP responsive element binding protein 5)
Diseases named in the same sentence as CREB5 in open-access papers (continued):
Sharing a sentence is not in itself a finding about the gene and the disease.
tumor (continued). "Overexpression of CREB5 promoted tumor growth and resulted in greater tumor weight." (PMID 35773668, 2022). "Additionally, the downregulation of S100B, IL31RA, and CREB5 found here may also promote anti-tumor responses and reduce tumor progression." (PMID 37762335, 2023). "Thus, in this manuscript, we further explored whether circVAPA silencing could exert the anti-tumor effect in CRC cells through modulating miR-125a/CREB5 axis." (PMID 32256212, 2020). "Moreover, relevant literature exhibited that CREB5 could work as the tumor-promoting effect through expediting proliferation, metastasis, migration and hampering apoptosis in CRC." (PMID 32256212, 2020). "We determined that CREB5 is a key regulator of basal and SCL transcriptional programs and tumor-forming phenotypes in PC." (PMID 41954995, 2026). "Other pathways, such as Ras (RAF1, RALBP1, RASSF1), TGF-β (CREB3L2/3, CREB5, TCL1A), Rap1, Hippo, and axonal guidance, further facilitate tumour migration and spread." (PMID 41007296, 2025). "CREB5 has an effect similar to that of VHL; under hypoxic conditions, CREB5 promotes tumor angiogenesis." (PMID 38191389, 2024). "MiR-29c inhibits tumor growth by regulating TGFB-induced factor homeobox 2 (TGIF2), CAMP-responsive element binding protein 5 (CREB5), and V-Akt murine thymoma viral oncogene homolog 3 (AKT3)." (PMID 37298314, 2023). "First, we found that both CREB5 and TOP1MT were significantly higher in tumor tissues than in the normal control." (PMID 35773668, 2022). "Simultaneous infection of stromal and tumor cells; Upregulation of Fez1 and Pycard; Downregulation of DLL-4, Angiopoietin 2, PECAM, Tie-1, and FOS EGR2, CREB-5, IL-6, Map2K1, CCL22, TIMD4 and CCL19." (PMID 35640930, 2022). "Cholesterol-modified siCREB5 and siTOP1MT were used to silence the expression of CREB5 and TOP1MT in the xenograft tumor models." (PMID 35773668, 2022). "Since CREB5 promoted ART-resistant activity, we anticipated CREB5 interactions at ARBs would be enriched in tumor-specific binding sites." (PMID 35550030, 2022). "On the contrary, proliferation-promoted genes such as CTNNB1, CREB1, CREB5, and TCF7L2 were up-regulated 3.65-, 2.63-, 2.87-, and 5.75-fold respectively in tumor tissues." (PMID 23285163, 2012). "In vitro experiments including migration assay, wound-healing assay, chicken chorioallantoic membrane assay, and human umbilical vein endothelial cells tube formation assay were used to investigate the effects of CREB5 on CRC cell migration and tumor angiogenesis ability." (PMID 32843066, 2020). "Additionally, a gene set enrichment analysis (GSEA) plot showed significant enrichment of tumor-related genes and CRC-related gene sets in the high-CREB5 expression group." (PMID 32843066, 2020). "From these six genes two were higher expressed in GAMs derived from the RCAS model (CD300lf and Cd200r4), two genes were expressed at similar levels in GAMs in both tumor models (Trem1 and Sh2d1b1), and two genes were higher expressed in GAMs derived from the GL261 model (Uck2 and Creb5)." (PMID 25658639, 2015). "Little is known about the specific pathways regulated by CREB5, however ATF3 is known to mediate repression of inflammatory signals, and may function as an oncogene or tumor suppressor depending on cell type and context." (PMID 23935999, 2013). "Further experiments demonstrated that the upregulation of CREB5 and the negative correlation between miR‐211‐5p and CREB5 were detected in HCC tumor tissues." (PMID 36565037, 2023). "To verify whether CREB5 conferred cisplatin resistance in vivo, we subcutaneously injected HN30 expressing with or without CREB5 into nude mice to establish xenograft tumor models." (PMID 35773668, 2022).
cancer (19 papers, 2020 to 2025). A tumor composed of atypical neoplastic, often pleomorphic cells that invade other tissues. "CREB5 expression was also associated with histological grade, residual cancer, and vascular invasion." (PMID 39915455, 2025). "On the other hand, RNA-seq data showed that four other genes (DUSP6, NFIX, VIM, and SPARCL1) associated with cancer were also downregulated in CREB5 knockdown cells." (PMID 38418476, 2024). "As a diagnostic marker, CREB5 is valuable in assessing the prognosis of cancer patients." (PMID 35773668, 2022). "It is reported that the overexpression of cAMP-responsive element binding protein 5 (CREB5) promotes the proliferation and migration of different cancer cells." (PMID 35754483, 2022). "These CREB5 transcriptional co-factors are potential therapeutic targets to perturb CREB5 signaling in cancers that upregulate its activity." (PMID 35550030, 2022). "The therapeutic effect of nizatidine was mediated by two complementary mechanisms:Hepatocytes/parenchymal cancer cells: we demonstrate that the HRH2/CREB5 signaling pathway is perturbed in hepatocytes during liver injury." (PMID 34535664, 2021). "Previous studies have revealed that CREB5 mRNA was upregulated in CRC as demonstrated by bioinformatics analysis or qRT-PCR examination in human cancer tissues." (PMID 32843066, 2020). "Examination of TCGA pan cancer datasets revealed frequent CREB5 amplification and overexpression in kidney cancers, sarcomas, lymphomas, and lung adenocarcinomas as well as glioblastomas and gliomas." (PMID 32843066, 2020). "CREB5 is known to be upregulated in various cancers, and promote invasiveness and metastasis." (PMID 39171503, 2024). "In addition to the receptors FGFR1, FGFR4 and ERBB4, the main effector AKT1 and its downstream effectors, MTOR, GSK3B, p21, WEE1, BAD and CREB5, which mediate cancer cell growth and progression, also exhibited marked changes in HPV-ind CCs." (PMID 38253702, 2024). "Prior works have reported the roles of CREB5 in several types of cancers." (PMID 37816820, 2023). "Furthering the understanding of these underlying changes may inform of additional research avenues and precision strategies for advanced cancer patients that depend on CREB5." (PMID 35550030, 2022). "The mechanisms by which CREB5 promotes progression of mCRPC or other cancers remains elusive." (PMID 35550030, 2022). "Altogether, these studies implicate pro-tumor CREB5 functions in cancers." (PMID 35550030, 2022). "For example, cancer-related genes CREB5 and LMNTD1 are associated with BSA, but are not related to the lifestyles used in this study." (PMID 34143809, 2021). "Recent studies revealed the roles of CREB5 in the development and progression of cancers." (PMID 32843066, 2020). "Moreover, CREB5 and LMNTD1 genes are associated with cancer." (PMID 34143809, 2021). "CAMP responsive element binding protein 5 (CREB5) is a transcription factor and has been shown to play a key role in the development and progression of various cancers." (PMID 39915455, 2025). "Importantly, while many of the genes affected by epigenetic priming are not necessarily cancer drivers, in the case of hypomethylated/upregulated genes such as UBD and CREB5, these genes have been linked to prognosis and disease outcome." (PMID 34863035, 2022).
infection (5 papers, 2014 to 2022). The state of being infected such as from the introduction of a foreign agent such as serum, vaccine, antigenic substance or organism. "Infection of SZCs with lentivirus encoding an shRNA directed against the 3′UTR of Creb5 substantially diminished these protein levels." (PMID 33712729, 2021). "Indeed, infection of SZCs with lentivirus encoding Cas9 plus the Creb5 gRNA resulted in decreased levels of Creb5 protein." (PMID 33712729, 2021). "Overall, these results demonstrate that miR-876-5p can regulate the EV-A71 infection cycleby targeting the CREB5 host factor." (PMID 32024541, 2020). "We also evaluated the role of miR-876-5p in the EV-A71 infection cycle by CREB5 mediated by transfection with an anti-miR-876-5P inhibitor or in combination with an si-CREB5 plasmid." (PMID 32024541, 2020). "Next, we evaluated whether the role of miR-876-5p in the EV-A71 infection cycle is mediated by CREB5." (PMID 32024541, 2020). "In the present study, we provided evidence that miR-876-5p participates in the EV-A71 infection cycle through targeting CREB5 in SF268 cells, opening up a new application tool for circulating miRNAs in the EV-A71 infection." (PMID 32024541, 2020). "In this study, we provide evidence that miR-876-5p participates in the EV-A71 infection cycle by targeting CREB5 in SF268 cells, and we demonstrate that miR-876-5p regulates viral replication by targeting CREB5 protein because CREB5 protein plays an inhibitory role in the EV-A71 infection cycle." (PMID 32024541, 2020).
adenocarcinoma (1 paper, 2020). A common cancer characterized by the presence of malignant glandular cells. "IHC showed that CREB5 protein was weakly expressed in normal tissue but markedly increased in adenocarcinoma cells and was mainly localized in the nuclei." (PMID 32843066, 2020).
cardiovascular diseases (1 paper, 2024). "Our findings concerning Sema’s modulation of NR4a1 through the Creb5 pathway offer insights into potential treatments for cardiovascular diseases, paving the way for future research in this domain." (PMID 38834564, 2024).
CREB5 also shares sentences with these, for which no sentence is quoted: Stroke (2 papers); Abdominal obesity (1); acute kidney injury (1); acute myeloid leukemia (1); alopecia areata (1); Alzheimer disease (1); atherosclerosis (1); cardiac hypertrophy (1); cervical cancer (1); CNS disorders (1); cocaine addiction (1); colitis (1); colon cancer (1); colorectal tumors (1); degenerative diseases (1); diabetic kidney disease (1); endometriosis (1); heart failure (1); Hepatitis (1); Hypercholesterolemia (1); Knee Osteoarthritis (1); liver disease (1); liver fibrosis (1); myocardial infarction (1); nephrotic syndrome (1); oral squamous cell carcinoma (1); psychiatric disorder (1); spinal cord injury (1); virus infection (1).